RNU6-865P (RNA, U6 small nuclear 865, pseudogene)
Gene: Small nuclear RNA gene on chromosome 3 (100,952,627 to 100,952,733, forward strand). Ensembl gene ENSG00000201642.
Homologues: Orthologues: chimpanzee U6 (97% identical), macaque U6 (89% identical), pig U6 (78% identical), rat LOC120098447 (72% identical). Paralogues in human: RNU6-21P (87% identical), RNU6-39P (87% identical), RNU6-1 (86% identical), RNU6-1026P (86% identical), RNU6-2 (86% identical), RNU6-3P (86% identical), RNU6-4P (86% identical), RNU6-560P (86% identical), RNU6-5P (86% identical), RNU6-6P (86% identical), RNU6-7 (86% identical), RNU6-8 (86% identical), and 1287 more.